SDC1 (syndecan 1)
Diseases named in the same sentence as SDC1 in open-access papers (continued):
Sharing a sentence is not in itself a finding about the gene and the disease.
prostate carcinoma (continued). "Among the cell lines, syndecan-1 expression was much higher in the androgen independent prostate cancer cell lines DU145 and PC3, rather than the androgen-dependent LNCaP, suggesting that syndecan-1 might participate in the process of androgen-dependent to -independent conversion." (PMID 23691363, 2013). "The high sensitivity and specificity of the sortilin and syndecan-1 biomarkers offer a significant advantage over PSMA, as the latter has variable expression within cancer tissue and is not overexpressed in all prostate cancers." (PMID 41303628, 2025).
endothelial dysfunction (50 papers, 2018 to 2026). In vascular diseases, endothelial dysfunction is a systemic pathological state of the endothelium (the inner lining of blood vessels) and can be broadly defined as an imbalance between vasodilating and vasoconstricting substances produced by (or acting on) the endothelium. "High syndecan-1 was associated with host response changes, particularly those related to endothelial dysfunction, followed by inflammation and coagulation." (PMID 42312022, 2026). "Occult hypoperfusion (associated with elevated plasma soluble thrombomodulin and syndecan-1, indicating shock-induced endothelial dysfunction) can occur in the setting of normal vital signs." (PMID 40576680, 2025). "While SDC1 has been previously associated with endothelial dysfunction and metabolic dysregulation, our findings provide detailed insights into its specific role within this particular population." (PMID 41039734, 2025). "In HFpEF patients, increased circulating levels of syndecan-1, a glycocalyx shedding biomarker, were associated with endothelial dysfunction and a doubling of plasma syndecan-1 levels increased risk of all-cause mortality and rehospitalisation." (PMID 32451732, 2020). "Since endothelial dysfunction is linked to leukocyte infiltration into surrounding tissues and the loss of vascular integrity and permeability, we also evaluated the circulating levels of syndecan-1, a biomarker of endothelial glycocalyx shedding." (PMID 34576076, 2021). "Importantly, a decrease in Sdc1 mRNA is associated with endothelial dysfunction, a hallmark of the endotheliopathy of trauma." (PMID 32978505, 2020). "Given that MMP-9 is also elevated in other pathologic conditions such as inflammation, ischemia, and diabetes, our results suggest that MMP-9–mediated syndecan-1 loss could be a common pathway contributing to endothelial dysfunction across multiple retinal disease contexts." (PMID 40981101, 2025). "We focused our research on depicting the potential use of syndecan-1 in clinical practice as a diagnostic and prognostic biomarker in patients presenting with phenomena suggestive of acute HF, especially from the perspective of systemic comorbidities and endothelial dysfunction." (PMID 37109427, 2023). "Endpoints assessed included mean changes in plasma inflammatory markers (IL-1β, IL-6, and TNF-α) and endothelial dysfunction markers (syndecan-1), handgrip strength, fatigue scale, and quality of life (QoL)." (PMID 41753154, 2026). "Plasma levels of the markers of endothelial dysfunction angiopoietin-2, syndecan-1, and Vascular cell adhesion molecule 1 (VCAM-1) show a moderate positive correlation with PD-1 expression in CD4+ T-cells (shown for TP2)." (PMID 40595657, 2025). "This evidence positions SDC1 as a key mediator in the vicious cycle of endothelial dysfunction, systemic inflammation and metabolic disturbances that characterise MetS." (PMID 41039734, 2025). "Similar to what we observed for PD-1, the frequencies of CD4+/CD8+ T-cells expressing these inhibitory receptors correlate positively with endothelial dysfunction and severity-related plasma markers (syndecan-1, VCAM-1, and ferritin)." (PMID 40595657, 2025). "In patients with yellow fever, elevated YFV NS1 and syndecan-1 serum levels correlated with disease severity, endothelial dysfunction, viral load, and mortality." (PMID 40585555, 2025). "The syndecan-1′s potential use in clinical practice is further based on its preserved ability as an early marker of fibrosis and a direct indicator of endothelial dysfunction in asymptomatic patients, with incipient and subclinical HF." (PMID 37109427, 2023). "Despite there being some data in the literature supporting the use of syndecan-1 as a marker of glycocalyx injury and endothelial dysfunction, the results on its role in acute HF are extremely scarce." (PMID 37109427, 2023). "Syndecan-1 and endocan are two main markers of glycocalyx damage, used to detect endothelial dysfunction in serum or plasma." (PMID 37542221, 2023).
endothelial dysfunction (continued). "A recent study presented that elevated plasma concentrations of syndecan-1 and hyaluronan in patients with end-stage chronic kidney disease decreased three months after kidney transplantation, suggesting the regression of endothelial dysfunction." (PMID 38002579, 2023). "The correlation between the expression of endothelial dysfunction biomarker Syndecan-1, free indoxyl sulfate, and total p-cresyl glucuronide on one side, and miR-126 on the other side was confirmed using multivariate analysis." (PMID 34638892, 2021). "Syndecan-1 has correlated with baseline endothelial dysfunction and the skeleton of endothelial glycocalyx." (PMID 33785732, 2021). "Increased heparanase activity correlated with the endothelial dysfunction markers heparan sulfate and syndecan-1, as well as clinical markers of plasma leakage such as ascites, hematocrit concentration and gall-bladder wall thickening." (PMID 34987504, 2021). "PBR values and syndecan-1 concentrations correlated moderately not only with each other (rs = 0.50 [95% CI 0.10–0.76], p = 0.02), but also with further markers of endothelial dysfunction and injury (Figure E1: Online Supplement)." (PMID 33058027, 2021). "Plasma endothelial dysfunction and injury biomarkers, including angiopoietin-2, soluble vascular endothelial cadherin (sVE-cadherin), endocan and syndecan-1, were measured at study enrollment." (PMID 33541396, 2021). "Numerous studies have identified shed syndecan-1 as a marker of both endothelial dysfunction and glycocalyx degradation, an example being ischaemia-reperfusion injury." (PMID 33561383, 2021). "The field of clinical monitoring of endothelial dysfunction has been limited to assessing reactive hyperemia, therefore the use of SDC1 as a potential biomarker of endothelial injury has been of great interest." (PMID 33013880, 2020). "TBI patients with EoT+ (syndecan-1 ≥ 40 ng/ml) exhibit marked endothelial dysfunction, physiological and coagulation derangements, and a higher frequency of complications." (PMID 30463625, 2018). "Recently, it has been demonstrated that syndecan-1, a biomarker of endothelial glycocalyx damage, is increased in nephrotic patients with near-normal renal function and it is important to endothelial dysfunction in these patients." (PMID 30384404, 2018). "Recently, our group demonstrated that syndecan-1, a biomarker of endothelial glycocalyx damage, is increased in nephrotic patients with near-normal renal function and is involved in endothelial dysfunction in these patients." (PMID 30384404, 2018). "These molecules, often referred to as ‘shedases,’ mediate rapid GCX degradation by either promoting syndecan-1 ectodomain shedding or by enzymatically cleaving heparan sulfate chains from their core proteins (heparinase), leading to acute GCX loss and endothelial dysfunction." (PMID 41576046, 2026). "Furthermore, we used specific inhibitors to delineate the mechanistic involvement of syndecan-1 degradation and endothelial dysfunction." (PMID 40981101, 2025). "Syndecan-1 is a less studied biomarker in cardiovascular diseases; its assessment in patients with acute HF being potentially able to reflect the myocardial pathological changes, such as fibrosis, inflammation, endothelial dysfunction or global wall stress." (PMID 37109427, 2023). "Another aspect that supports the hypothesis that syndecan-1 is a potentially useful biomarker is related to endothelial dysfunction." (PMID 37109427, 2023). "SDC-1 promotes the recruitment of neutrophils by combining with chemokines released in the degradation process to increase the inflammatory response, leading to endothelial dysfunction and damage to the BBB." (PMID 36779062, 2023). "ELISA results showed NETs from TBI patients, especially those with coagulopathy, could significantly impair endothelial dysfunction by decreasing the expression of syndecan-1, thrombomodulin, and VWF." (PMID 36802340, 2023).
endothelial dysfunction (continued). "Elevated plasma syndecan-1 may not only serve as a biomarker for endothelial dysfunction and damage, but also contribute to a variety of pathophysiological functions." (PMID 36675479, 2023). "Endothelial dysfunction was assessed on admission by quantifying reactive hyperemia-peripheral arterial tonometry and plasma levels of endothelin-1, soluble E-selectin, endocan and syndecan-1." (PMID 33053025, 2020). "In septic patients with acute lung injury, respiratory distress syndrome or DIC, syndecan-1 and hyaluronan are elevated, and may serve as biomarkers to follow for evaluating therapies to improve vascular and endothelial dysfunction." (PMID 33375342, 2020). "We have been interested in the role of Sdc1 in endothelial dysfunction following hemorrhagic shock." (PMID 32978505, 2020). "Since in comparisons to other types of clinical situations, syndecan-1 was only slightly upregulated, endothelial dysfunction after major abdominal surgery might be overestimated." (PMID 32576151, 2020). "The present study found a high proportion of excess weight in adolescents (19.3%) and a significant correlation between renal function and endothelial damage, evidenced by syndecan-1 levels, indicating a possible subclinical kidney injury and endothelial dysfunction." (PMID 29340529, 2018). "Endothelial dysfunction induced by overexpression of miR-19b mimics in vitro was confirmed in vivo by pretreatment of hemorrhagic shock mice with miR-19b oligo inhibitor, which maintained Sdc1 expression and attenuated post-shock lung injury, inflammation and hyperpermeability." (PMID 32978505, 2020). "Other highlighted studies increased syndecan-1 levels amongst patients suffering from acute myocardial infarction (AMI), due to both adrenergic stimulation and ischemic-mediated endothelial dysfunction." (PMID 37109427, 2023). "In addition, high preoperative syndecan-1 may reflect baseline endothelial dysfunction." (PMID 32531891, 2020). "Following the statistical analysis, we observed a significant negative correlation between syndecan-1 and HDL-cholesterol, virtually confirming the role of HDL deficiency in endothelial dysfunction." (PMID 37109427, 2023). "In our study, ELISA results validated that syndecan-1, soluble thrombomodulin, and VWF were positively correlated with NET markers, which indicated that NETs may participate in endothelial dysfunction in TBI." (PMID 36802340, 2023). "Endothelial dysfunction has been reported to participate in TIC, and plasma samples from severely injured patients on admission exhibited increased levels of syndecan-1, which correlated with increased activated protein C (APC), prolonged PTT, and elevated epinephrine levels." (PMID 35004604, 2021). "Syndecan-1, NIRS and FMD may be complementary means to investigate the same problem: global endothelial dysfunction." (PMID 32576151, 2020). "Third, the lack of a positive control (i.e. patients with significant endothelial dysfunction and EG disruption) is a limit and prevented the ability to demonstrate any significant correlation between syndecan-1 concentrations, StO2-reperfusion slope and FMD-max, as initially hypothesised." (PMID 32576151, 2020).
hepatocellular carcinoma (41 papers, 1999 to 2025). A malignant tumor that arises from hepatocytes. "Loss of epithelial SDC1 is associated with poor prognosis in hepatocellular carcinoma, colorectal cancer, and gastric cancer patients, together with high tumor volume and high histological grade." (PMID 38048216, 2023). "The same conclusion that loss of syndecan-1 expression is a characteristic feature of high metastatic potential has also been proven to be applicable to human hepatocellular carcinoma (HCC)." (PMID 30135409, 2018). "This loss of syndecan-1 promotes a TGFβ (Transforming growth factor β)-dependent EMT that is implicated in hepatocellular carcinoma metastasis." (PMID 28241498, 2017). "Syndecan-1 is expressed in human normal liver and the loss of syndecan-1 expression is a typical feature of hepatocellular carcinoma with high metastatic potential, where syndecan-1 expression is reduced both at mRNA and at protein levels." (PMID 26420915, 2015). "Furthermore, overexpression of syndecan-1 in hepatoma cells is associated with a shift of heparan sulfate structure toward a highly sulfated type specific for normal liver." (PMID 32977498, 2020). "Syndecan-1 is a very promising biomarker, being correlated not only with the degree of cardiac fibrosis but also with the severity of liver fibrosis and long-term risk of hepatic carcinoma." (PMID 31815014, 2019). "The presence of syndecan-1 is associated with favorable outcomes in both lung cancer and mesothelioma, and the loss of syndecan-1 is a feature of hepatocellular carcinoma with high metastatic potential." (PMID 26869927, 2016). "Research has demonstrated that SDC1 fosters cisplatin resistance in hepatocellular carcinoma cells via the PI3K-AKT pathway." (PMID 41209699, 2025). "As a result, syndecan-1 levels are elevated in most pathologies evolving with liver fibrosis, such as non-alcoholic steatohepatitis, liver cirrhosis or hepatocellular carcinoma." (PMID 37109427, 2023). "Our previous experiments indicated that SDC1, the major proteoglycan of the liver, is capable of inducing hepatocyte-like differentiation of hepatoma cell lines, and HS chains in the healthy human liver can interfere with DNA-binding transcription factors." (PMID 33801718, 2021). "Consistent with this notion, overexpression of full-length or extracellular domain-truncated syndecan-1 in human hepatoma cell lines resulted in cell differentiation via downregulation of the transcription factors Ets-1 and AP-1." (PMID 33801718, 2021). "Our previous in vitro experiments revealed that transfection of human syndecan-1 (hSDC1) into hepatoma cells, initiating hepatocyte-like differentiation." (PMID 33801718, 2021). "To confirm the implication of downregulated Ets-1 in the partial differentiation and suppressed proliferation of hepatoma cells overexpressing syndecan-1, we knocked down Ets-1 expression by miRNAs." (PMID 32977498, 2020). "Changes in cell morphology appeared more markedly in hepatoma cells overexpressing the truncated form of syndecan-1." (PMID 32977498, 2020). "Future studies are needed to complement our results by determining additional effects of syndecan-1, either full-length or truncated, on the phenotype and behavior of hepatoma cells." (PMID 32977498, 2020). "We found that syndecan-1 proved to be a good marker for hepatitis C virus based hepatocellular carcinoma and increased with liver dysfunction." (PMID 30826971, 2020). "In the different primary liver diseases like liver fibrosis or hepatocellular carcinoma we have found elevated syndecan-1 levels." (PMID 30826971, 2020). "As a result, cell proliferation and proteolytic shedding of syndecan-1 from the cell surface are restrained, which facilitates redifferentiation of hepatoma cells to a more hepatocyte-like phenotype." (PMID 32977498, 2020). "The amount of syndecan-1 in liver carcinoma samples depended on the previous pathology of the organ." (PMID 30826971, 2020).
hepatocellular carcinoma (continued). "Our other research work had demonstrated the correlation of SDC1 with ANPEP expression that affected stemness characteristics of hepatoma cells." (PMID 32756007, 2020). "The proliferation rate of truncated syndecan-1 transfectants decreased significantly in both hepatoma cell lines (Student’ t-test, HepG2 p < 0.001 and Hep3B p < 0.001)." (PMID 32977498, 2020). "Previous studies have revealed that SDC1 has prognostic value in various types of cancers such as hepatocellular cancer, gastric cancer, lung cancer, and colorectal cancer." (PMID 29340066, 2017). "In the liver, SDC1 levels are the highest in liver cirrhosis and hepatocellular carcinoma." (PMID 38791454, 2024). "Hepatocellular carcinoma cell lines are platinum-resistant when syndecan-1 (SDC1) is upregulated." (PMID 38048216, 2023). "Wild-type (WT) and hSDC1+/+ mice were exposed to diethylnitrosamine (DEN)-induced hepatocarcinogenesis to investigate whether targeted overexpression of syndecan-1 in the liver is capable of delaying the development of hepatocellular cancer." (PMID 33801718, 2021). "Our previous results confirmed that the differentiation of hepatoma cell lines after syndecan-1 transfection acted together with the changes of an HS pattern to a more sulfated one, as indicated by HS-specific antibodies, capable of interfering with the promoter activation of AP1 and Ets1." (PMID 33801718, 2021). "Intriguingly, strong expression of syndecan-1 can also confer aggressive behavior to some tumor types as reported in dedifferentiated thyroid, poorly differentiated prostate, high grade breast, high grade ovarian, and high grade hepatocellular carcinomas." (PMID 32977498, 2020). "In this study, we demonstrate that re-expression of full-length or ectodomain-deleted syndecan-1 in hepatocellular carcinoma cells downregulates phosphorylation of ERK1/2 and p38, with the truncated form exerting an even stronger effect than the full-length protein." (PMID 32977498, 2020). "The most prominent enhancement of syndecan-1 expression could be observed in cirrhosis based hepatocellular carcinoma and cirrhosis." (PMID 30826971, 2020). "Interestingly, the treatment of MCF-7 cells with hepatoma-derived exosomes reduced both the levels of SDC1 mRNA and protein expression." (PMID 29963269, 2018). "Recent studies have demonstrated that EMT of hepatocellular carcinoma cells involves S1P/S1P1-dependent phosphoinositol-3-kinase (PI3K)/PKB activation and increased expression of metalloproteinase 7 (MMP7) and shedding and loss of syndecan-1." (PMID 28241498, 2017). "However, the clinical data regarding syndecan-1 in patients with hepatocellular carcinoma (HCC) are scarce and controversial." (PMID 22396913, 2012). "Similarly, CCL2-induced human hepatoma cell migration and invasion has been blocked by anti-syndecan-1 and -4 antibodies, but also when hepatoma cells were pretreated with heparitinases that remove glycosaminoglycans from cell surfaces." (PMID 22505933, 2012). "Previously, we revealed that the expression of syndecan-1 was reduced in human hepatocellular carcinomas with high metastatic potential and speculated that syndecan-1 played an important role in inhibition of invasion and metastasis." (PMID 10507762, 1999). "Moreover, SDC1 could serve as a prognostic biomarker for various cancers, such as hepatocellular carcinoma, gastric cancer, laryngeal cancer, and squamous cell lung carcinoma." (PMID 35087751, 2021). "Meanwhile, the endogenous expression of TGFβ1 was tightly mediated by MMP-7, thus constituting an MMP-7/syndecan-1/TGFβ1 autocrine loop to mediate hepatocellular carcinoma (HCC) metastasis." (PMID 31822964, 2020). "Prior studies have demonstrated that TGF-β signaling in hepatocellular carcinoma induces MMP-7 and heparanase, promoting syndecan-1 shedding and enhancing fibrogenic signaling." (PMID 40572724, 2025).